INS (insulin)
Diseases named in the same sentence as INS in open-access papers (continued):
Sharing a sentence is not in itself a finding about the gene and the disease.
type 1 diabetes (continued). "Type 1 diabetes is an autoimmune disease in which insulin-producing beta cells in pancreatic islets undergo immune destruction, ultimately resulting in hyperglycemia." (PMID 35874740, 2022). "Up to one third of children and adolescents with type 1 diabetes injected rapid-acting insulin analogues after a meal." (PMID 36556278, 2022). "Body mass index, daily insulin doses and sensor data of children and adolescents with type 1 diabetes using the advanced hybrid closed-loop system at initiation of the system, at 6 months and 1 year of follow-up." (PMID 36303875, 2022). "Previous studies have shown that date palm seeds induce immunity in broiler chickens, cause an increase in the paraoxonase and arylesterase activities in hypercholesterolemic rats and enhance the endogenous insulin secretion in type 1 diabetic rats." (PMID 35291987, 2022). "Type 1, or insulin-dependent diabetes, is an autoimmune disease characterized by the destruction of insulin-producing pancreatic β cells in the islets of Langerhans leading to insulin deficiency." (PMID 35630078, 2022). "Similar to insulin, glucose metabolism is critical for brain development and function, and abnormal glucose in children with type 1 diabetes has a greater detrimental effect on central nervous system development." (PMID 36483136, 2022). "In women with type 1 diabetes, adequate reduction in the insulin dose immediately after pregnancy and when indicated is also important to limit the need for extra carbohydrate intake for hypoglycaemia." (PMID 36432552, 2022). "For patients with type 1 diabetes, the treatment of insulin in multiple doses is mandatory from the diagnosis; these patients have no treatment alternatives." (PMID 36556420, 2022). "Children with type 1 diabetes, in comparison to their healthy peers, are challenged more frequently with depressive and anxiety disorders, which can be insulin-induced and lead to their poor metabolic control and lower quality of life." (PMID 36429590, 2022). "In type 1 diabetes, the pancreas is unable to produce insulin due to the destruction of the beta-cells that can produce this hormone." (PMID 36012115, 2022). "We documented a cross-sectional baseline description of 99 adults with type 1 diabetes and problematic hypoglycaemia despite structured education in flexible insulin therapy." (PMID 35325258, 2022). "A correct diagnosis is important to determine the appropriate treatment, with type 1 diabetes requiring physiological doses of insulin replacement to avoid acute life-threatening complications such as diabetic ketoacidosis." (PMID 35994083, 2022). "Type 1 diabetes is a polygenic disease that results in an autoimmune response directed against insulin-producing beta cells." (PMID 36497105, 2022). "Specifically, artificial pancreas-like closed-loop insulin delivery systems are some of the most promising devices for substituting for endogenous insulin secretion in type 1 diabetes patients." (PMID 35577814, 2022). "Type 1 diabetes (T1D) is a chronic disorder characterized by immune-mediated destruction of pancreatic insulin-producing β-cells." (PMID 35464488, 2022). "Type 1 diabetes (T1D) is an autoimmune disease that results in the destruction of insulin producing pancreatic β-cells." (PMID 36289205, 2022). "Treatment and management of type 1 diabetes requires daily injections of insulin and constant blood glucose monitoring, healthy diet, and exercise." (PMID 35055576, 2022). "Although insulin pump therapy is an important treatment modality for patients with type 1 diabetes, rates of pump use appear to vary broadly internationally." (PMID 35757419, 2022). "This will be the largest randomized controlled trial to evaluate the impact of closed-loop insulin delivery during type 1 diabetes pregnancy." (PMID 35382796, 2022).
type 1 diabetes (continued). "Frederick Banting, Charles Best and James Collip’s transformative discovery of insulin in 1921 has given millions of individuals with type 1 diabetes a second chance at life." (PMID 35994083, 2022). "Even more convincing was a study in which physiologic insulin delivery in patients with type 1 diabetes was compared to a constant infusion of insulin." (PMID 35163806, 2022). "Evidence suggests that between 30-40% of patients with type-I diabetes suffer from one to three episodes of hypoglycemia (insulin excess) per year." (PMID 36064616, 2022). "Type 1 diabetes is an autoimmune disorder, developed by the destruction of insulin-producing β-cells in the endocrine pancreas." (PMID 36144750, 2022). "Usage of insulin pumps is still relatively low (roughly 10% of patients having type 1 diabetes) but is rising along with the closed loop usage." (PMID 36130979, 2022). "Very limited data exist about the use of closed-loop insulin delivery systems during type 1 diabetes pregnancy." (PMID 36422278, 2022). "The aim of this systematic review was to report the evidence on optimal prandial timing of insulin bolus in youths with type 1 diabetes." (PMID 36556278, 2022). "Islet transplantation in dogs with type I diabetes resulted in up to a 50% reduction in insulin dose and improved glycemic control 6 months post-implantation." (PMID 35769100, 2022). "Mauriac syndrome was first described in 1930, in children with type I diabetes treated with rapid-acting insulin, displaying the classical presentation of hepatomegaly with distended abdomen, growth delay, and delay in puberty." (PMID 35655318, 2022). "One of these reviews having 49 randomized clinical analyses, compared an insulin preparation having fast action with regular human insulin, notable average variation of 0.1% in HbA1c was identified as endorsing preparations in subjects with type-I diabetes." (PMID 35723344, 2022). "In type 1 diabetes (T1D) endogenous insulin-secretion is lost due to beta-cell destruction and affected subjects are dependent on exogenous insulin administration." (PMID 36315525, 2022). "Effect of initiating use of an insulin pump in adults with type 1 diabetes using multiple daily insulin injections and continuous glucose monitoring (DIAMOND): a multicentre, randomized controlled trial." (PMID 35118826, 2022). "Type-I diabetes mellitus involves the synthesis and secretion of insulin from β-cells which become deteriorated through the immune system." (PMID 35723344, 2022). "Another survey that was conducted in Chinese children with type 1 diabetes between 2012 and 2015 from 25 major cities reported 15.21% of patients receiving insulin pump therapy." (PMID 35757419, 2022). "In 45 patients with non-insulin-dependent diabetes, the administration of hesperidin at 500 mg/day for 8 weeks can lead to an increment in insulin content and a potential reduction of fast blood glucose content." (PMID 36557843, 2022). "The weight reduction was usually seen after detemir therapy compared with the NPH insulin, an important feature of detemir insulin in individuals with type-I diabetes." (PMID 35723344, 2022). "Type 1 diabetes (T1D) is a chronic autoimmune disorder characterized by the selective destruction of insulin-secreting pancreatic β cells." (PMID 35739935, 2022). "The proportion of “Case exclusion” (with specific type 1 diabetes diagnosis codes) on insulin was also the highest with the highest percentage of starting insulin within the first year of diagnosis." (PMID 35769930, 2022). "Prior prospective studies trialling interventions while following iAb positive high risk individuals for developing type 1 diabetes have shown a very low DKA at overt type 1 diabetes onset as well as lower HbA1c and insulin requirements at diagnosis." (PMID 35185797, 2022).
type 1 diabetes (continued). "DIY AID does not remove the requirement for user input in the management of type 1 diabetes; understanding of carbohydrate counting, insulin:carbohydrate ratios and insulin sensitivity factors, the technology alone is not enough." (PMID 35951597, 2022). "Regenerative therapy using stem cells that regenerate beta cells would be a promising approach to cure type 1 diabetes, in which insulin-producing pancreatic beta cells are damaged." (PMID 36267277, 2022). "Type 1 diabetes is a chronic disease characterized by the autoimmune destruction of pancreatic beta cells, which are responsible for insulin secretion." (PMID 35577814, 2022). "Whereas in some autoimmune disease specific antigen targets can be identified (e.g., insulin in type 1 diabetes), in other subtypes, including systemic sclerosis, the lack of one single autoantigen represents an obstacle for CAR-T cells’ efficacy." (PMID 36359742, 2022). "Type 1 diabetes (T1D) is characterized by the immune-mediated destruction of insulin-producing β cells." (PMID 35015736, 2022). "Their average Type 1 diabetes duration was 3.91 (SD = 2.77) years, and 76.3% were currently using an insulin pen for insulin injection." (PMID 35492685, 2022). "In this systematic review and meta-analysis, we found that inhaled insulin is equally effective as subcutaneously administered insulin in patients with Type 1 Diabetes." (PMID 35509734, 2022). "Artificial pancreas systems have started to become widely used by a new population of patients with type 1 diabetes to mimic natural insulin production." (PMID 35577814, 2022). "One of the chronic autoimmune diseases is type 1 diabetes (T1D) in which insulin-producing beta-cells in the pancreas are destroyed, resulting in chronic high blood sugar." (PMID 35697707, 2022). "Type 2 diabetes known as non-insulin dependent diabetes is characterizedby inefficient use of the insulin produced by the beta cells of the pancreas and it accounts for 90% cases." (PMID 36420434, 2022). "A nationwide survey in Brazil Adherence to insulin therapeutic regimens in patients With type 1 diabetes." (PMID 35195219, 2022). "Type 1 also known as insulin-dependent diabetes is characterized by insufficiency of theproduction of insulin as a result of damage of the beta cell of the pancreas." (PMID 36420434, 2022). "Type 1 diabetes (T1D) mellitus is characterized by the destruction of insulin-producing pancreatic beta cells, leading to insulin deficiency and increased glucose levels in blood and urine." (PMID 35208726, 2022). "A review of potential adjuvant pharmacological therapies to insulin in obese patients with type 1 diabetes." (PMID 35784568, 2022). "Oscillospiraceae family negatively correlates with BMI and anti-insulin autoantibodies in type 1 diabetes in children." (PMID 35574036, 2022). "Insulin is considered to be a key antigenic target of T cells in Type 1 Diabetes (T1D) and autoimmune diabetes in the NOD mouse with particular focus on the B-chain amino acid sequence B:9-23 as the primary epitope." (PMID 36032090, 2022). "Destructions of pancreatic β cells engendered the lower secretion of insulin, thereby resulting in type I diabetes, which is insulin dependent." (PMID 35956982, 2022). "Type 1 diabetes is an autoimmune condition characterised by immune-mediated destruction of pancreatic beta-cells, leading to lifelong dependency on insulin therapy." (PMID 35585600, 2022). "Type 1 diabetes (T1D) is characterized by immune-mediated destruction of the insulin-secreting β-cells of the pancreas." (PMID 36316364, 2022). "Over time, however, the beta cells of the pancreas lose the ability to produce sufficient insulin, increasing the dependence on exogenous insulin and making this insulin resistant disease more similar to type 1 diabetes." (PMID 36703927, 2022).
type 1 diabetes (continued). "Although inflammation and the dysregulation of insulin signaling are thought to be mechanistic factors of DPN, few studies have explored their detailed associations with the pathophysiology of DPN in type 1 diabetes (T1D)." (PMID 36477360, 2022). "The influence of glucose and insulin is examined during hyperglycemic clamps in individuals with prediabetes and in euglycemic hyperinsulinemic clamped patients with type 1 diabetes." (PMID 36127330, 2022). "Type 1 diabetes (T1D) is a chronic autoimmune metabolic disorder with onset in pediatric/adolescent age, characterized by insufficient insulin production, due to a progressive destruction of pancreatic β-cells." (PMID 36555624, 2022). "Type 1 diabetes management is particularly challenging in very young children due to rapid physical and social development, hypoglycemia unawareness, high insulin sensitivity, and unpredictable food intake and activity patterns." (PMID 35561092, 2022). "Although the knowledge of the FIT parameters is crucial for medical practitioners, these parameters are usually omitted by the scientific community when deriving new models for insulin-glucose dynamics in type 1 diabetes cases." (PMID 35577814, 2022). "IFN-γ, IL-1β, and TNF-α production by autoreactive Th1 cells is involved in the destruction of insulin-secreting β-cells in type 1 diabetes." (PMID 35652039, 2022). "Currently, patients with type 1 diabetes can be controlled by injecting insulin and taking drugs to alleviate the disease." (PMID 36501537, 2022). "Type 1 diabetes, formerly known as juvenile diabetes, is an autoimmune disorder due to the pancreas’s inability to produce enough, or any, insulin." (PMID 35591223, 2022). "Altogether, these results indicate that the STZ treatment successfully induced a model of type 1 diabetes in the treated mice and that the insulin treatment improved the glucose homeostasis in the diabetic mice expectedly." (PMID 35524739, 2022). "In this systematic review and meta-analysis, we presented the assessment of evidence from thirteen randomized control trials, to evaluate the effectiveness of inhaled insulin in comparison to conventional insulin in patients diagnosed with type 1 diabetes." (PMID 35509734, 2022). "Previous studies indicated that sEH expression is decreased in liver and kidney and is rescued by insulin treatment in type I diabetes mice model." (PMID 35744996, 2022). "Type 1 diabetes iAb recognise five types: Glutamic Acid Decarboxylase (GADA), Islet Cell Cytoplasmic (ICA), Insulinoma-Associated-2/Tyrosine Phosphatase (IA-2A), Insulin (IAA) and, Zinc Transporter-8 Autoantibodies (ZnT8A)." (PMID 35185797, 2022). "Type 1 diabetes is a chronic disease characterized by autoimmune destruction of the insulin-producing beta cells of the pancreas resulting in absolute insulin deficiency." (PMID 35460036, 2022). "The promise of a cell-based solution for the treatment type 1 diabetes is driving exciting research in to producing cells that mimic native β cell glucose sensitivity and insulin secretion." (PMID 36550929, 2022). "During puberty there is an increase of hormones that affect insulin sensitivity and for some adolescents that struggle with type 1 diabetes during puberty, it can be difficult to find motivation." (PMID 36404844, 2022). "The eligibility criteria for study selection were randomized controlled trials comparing artificial pancreas systems (MPC, PID, and fuzzy algorithms) with conventional insulin therapy in type 1 diabetes patients." (PMID 36494830, 2022). "The mainstay of treatment for type 1 diabetes is intensive insulin therapy, either as multiple daily injections or continuous subcutaneous insulin infusion via pump." (PMID 35733769, 2022). "Type 1 diabetes is a chronic illness in which the native beta (β)-cell population responsible for insulin release has been the subject of autoimmune destruction." (PMID 35883588, 2022).
type 1 diabetes (continued). "Type 1 diabetes is also defined as juvenile diabetes or insulin-dependent diabetes as a patient’s pancreas is unable to manufacture or produce insulin." (PMID 35889889, 2022). "Current advanced technologies for the management of type 1 diabetes (T1D) include the following categories: insulin delivery systems, glucose-sensing technologies, and glucose-responsive insulin delivery systems." (PMID 35370980, 2022). "Iatrogenic hypoglycaemia is a continuous threat for most people with type 1 diabetes, occurring weekly or even daily as a consequence of treatment with insulin." (PMID 35867127, 2022). "mab287 is shown to block recognition of insulin by T cells and delay development of type 1 diabetes by at least 10 weeks." (PMID 35884798, 2022). "In patients with type 1 diabetes (T1D), compromised pancreatic β-cell functions are compensated through daily insulin injections or the transplantation of pancreatic tissue or islet cells." (PMID 35805883, 2022). "Type 1 Diabetes (T1D) is a globally rising autoimmune disease involving the dysfunction of pancreatic β-cells by the immune system, thus diminishing insulin production." (PMID 36136973, 2022). "An autoimmune reaction occurs when the body's defense system assaults the cells that make insulin, resulting in type-1 diabetes." (PMID 35875742, 2022). "In the streptozotocin-induced models of type 1 diabetes, insulin can prevent and reverse alterations of morphology, function, and gene expression patterns in bladder and prostate." (PMID 35545721, 2022). "Patients with insulin-dependent diabetes administrate exogenous insulin to control blood glucose levels." (PMID 35992127, 2022). "MxA was expressed exclusively in type 1 diabetes islets and was detected in 91.4% (64 of 70) of those islets with residual insulin immunopositivity." (PMID 35957810, 2022). "One recent survey from China reported the proportion of patients using insulin pumps to be as low as 15.21% among type 1 diabetes, which only included newly diagnosed children < 14 years of age." (PMID 35757419, 2022). "This is one of very few studies to describe the application of insulin pump therapy among type 1 diabetes in clinical practice in China." (PMID 35757419, 2022). "Results indicated that 6-weeks of voluntary wheel-running significantly improved insulin content (3-fold increased) and insulin secretion (3-fold increased) of pancreatic beta-cells in type 1 diabetic mice induced by STZ." (PMID 35742478, 2022). "For example, patients with type 1 diabetes need close blood sugar monitoring, titration of insulin and continuous diabetic education." (PMID 36062045, 2022). "One unexpected outcome of this study was that we also noted the presence of MDA5 positive, but somatostatin/insulin/glucagon immunonegative cells in type 1 diabetes cases." (PMID 35957810, 2022). "Intriguingly, deficiency of TLR9 was found to enhance glucose tolerance, and improve insulin sensitivity of type 1 diabetes." (PMID 35707851, 2022). "Type 1 diabetes (T1D) is a chronic condition resulting from the autoimmune destruction of insulin-producing β cells in the pancreas." (PMID 35214566, 2022). "Islet cell transplantation is a highly promising approach for treating type 1 diabetes aiming at reestablishing a physiological insulin secretion through replacement of the endocrine tissue." (PMID 35222280, 2022). "Type 1 diabetes (T1DM) is a consequence of the immune-mediated destruction of β-cells with consequent loss of the ability to produce and secrete insulin." (PMID 36359305, 2022). "In conclusion, combination therapy with cholecalciferol and lansoprazole for six months was associated with a slower decline in residual β-cell function and lower insulin requirements in children with new-onset type 1 diabetes." (PMID 36449759, 2022). "None of the previously published meta-analyses accounts for the effectiveness of inhaled insulin in patients diagnosed with type 1 diabetes." (PMID 35509734, 2022).